CD22 (CD22 molecule)
Diseases named in the same sentence as CD22 in open-access papers (continued):
Sharing a sentence is not in itself a finding about the gene and the disease.
autoimmune disease (continued). "The inhibitory function of CD22 and its restricted expression on B cells makes CD22 an attractive target for B-cell depletion in cases of autoimmune diseases and B-cell-derived malignancies." (PMID 28970495, 2017). "After the identification and screening, the effects of the optimal anti-CD22 Abs on the progression of autoimmune diseases and its potential immune mechanisms in regulating CD4+ T cells were explored in SLE mouse models." (PMID 23704998, 2013). "CD22 is a regulatory molecule that prevents the over-activation of the immune system and the development of autoimmune diseases." (PMID 19173745, 2009). "Treatment of mice with 1C5 ameliorates skin graft rejection and type 1 diabetes with expansion of regulatory γδ T cells probably through expansion of Breg cells, suggesting ligand interaction of CD22 as a novel target of therapy for autoimmune diseases and graft rejection." (PMID 41875099, 2026). "However, the recently reported structures of the IgM- and IgG-BCRs, and the BCR co-receptors CD19, CD81 and CD22 will help guide the rational design of antibodies, nanobodies, and miniproteins for the treatment of B cell malignancies and autoimmune diseases." (PMID 37296844, 2023). "Moreover, CD22 regulates the B cell response in autoimmune disease through regulation of BCRs and Tool-like receptors (TLRs)." (PMID 34276669, 2021). "CD22 is an inhibitory co-receptor of the B cell receptor that is exclusively expressed on B cells and is a regulatory molecule that prevents overactivation of the immune system and development of autoimmune diseases." (PMID 32977837, 2020). "CD22 deficiency alone does not lead to an autoimmune disease on pure C57BL/6 background, demonstrating a redundant function for B-cell Siglecs." (PMID 30559744, 2018). "Genome-wide association studies (GWAS) do not support CD22 as disease susceptibility locus in SLE or other autoimmune diseases; however it seems that polymorphisms in CD22 are relatively rare and variable between populations." (PMID 30323814, 2018). "Furthermore, CD22 has been shown to be a promising target in autoimmune diseases and B cell leukemias and it is expected that Siglec-10 will follow as a target in the future." (PMID 30559744, 2018). "A synthetic mouse CD22 mimetic with low micromolar affinity, Neu5Gcα2-6Galβ1-4GlcNAc with a 9-N-biphenylacetyl group, was synthesized with a lipid aglycone and formulated into liposomes along with antigens related to the target autoimmune diseases, inducing tolerance in vivo." (PMID 34065256, 2021). "However, a double deficient mouse, lacking both Siglec-G and CD22, develops systemic lupus-like autoimmune disease with age, demonstrating a partly redundant function of these two Siglecs on B cells." (PMID 30559744, 2018). "Since both CD20 and CD22 targets have shown activity with their respective antibodies given to patients with autoimmune disease, we postulated that a bispecific antibody (bsAb) targeting both antigens could have superior properties to either parental mAb alone or even a combination of both." (PMID 24841238, 2014). "LCAR-AIO is a trispecific CAR-T cell targeting CD19, CD20, and CD22, and its safety is being examined in phase I clinical trials for R/R SLE and other autoimmune disorders." (PMID 40862721, 2025). "Specifically, phosphorylated CD22 signals through the BCR to downregulate B cell activation that prevents the overactivation of the immune system and development of autoimmune disease." (PMID 34276669, 2021). "SM03 is a chimeric antibody that targets the B epitope of human CD22 antigen, and is currently in different phases of clinical trials in China for the treatment of non-Hodgkin's lymphoma (NHL), and other autoimmune diseases." (PMID 24816427, 2014). "The treatment against V-set Ig domain of CD22 would be a valuable therapeutic method for SLE and other autoimmune diseases." (PMID 23704998, 2013).
autoimmune disease (continued). "In conclusion, CD22 and Siglec-G are important inhibitory receptors on B cells that control the BCR signaling threshold, preventing a too strong B cell activation that may lead to autoimmune disease induction." (PMID 30559744, 2018). "The fact that deletion of Cd22 alone might not be sufficient to drive autoimmune disease in some mice can be explained by some functional redundancy between CD22 and Siglec-G, another Siglec family member, expressed on B cells also implicated in the regulation of BCR signaling." (PMID 30323814, 2018).
diffuse large B-cell lymphoma (25 papers, 2007 to 2026). "In this study, we engineered CD19/CD22 BS Loop CAR-T cells with an enhanced targeting efficacy for CD22 and assessed their safety and effectiveness in patients with relapsed/refractory diffuse large B-cell lymphoma." (PMID 41550973, 2026). "Clinical trials NCT04088890 and ChiCTR1800019298 showed safety and efficacy data for CD22-targeted CAR-T cells in patients with r/r high-risk large B-cell lymphoma (LBCL) and diffuse large B-cell lymphoma (DLBCL) after failure of CD19-targeted CAR-T therapy." (PMID 40726984, 2025). "Here, we report a 33-year-male with secondary central diffuse large B-cell lymphoma(CNSL) who develpoed double CRS following sequential infusion of Anti-CD22 and Anti-CD19 CAR T cells after autologous hematopoietic stem cell transplantation(ASCT)." (PMID 36798130, 2023). "Bi-specific anti-CD19/CD22 CAR T cell therapy has recently been spotlighted for its promising treatment of refractory diffuse large B cell lymphoma (DLBCL) compared to CD19 CAR T cell infusion, albeit the occurrence of CRS." (PMID 34514097, 2021). "Antibodies directed against CD22 have been used in radioimmunotherapy (RIT) clinical trials to treat patients with diffuse large B-cell lymphoma (DLBCL) with promising results." (PMID 32117707, 2020). "Recently, antibodies directed against CD22 have been used in RIT clinical trials to treat patients with diffuse large B-cell lymphoma (DLBCL) and B-cell acute lymphoblastic leukemia (B-ALL) with encouraging results." (PMID 32117707, 2020). "Polatuzumab vedotin (DCDS4501A) and pinatuzumab vedotin (DCDT2980S), MMAE-based ADCs targeting CD79b and CD22, respectively, showed clinical activity in combination with rituximab in relapsed/refractory diffuse large B-cell lymphoma (DLBCL)." (PMID 31159480, 2019). "Moreover, the Alexander trial administered CD19/CD22 dual-targeted CAR T cells plus pembrolizumab to 8 diffuse large B cell lymphoma (DLBCL) patients, with 75% ORR and 63% CR." (PMID 36091028, 2022). "We report a patient who underwent antiviral prophylaxis for 26 months and who discontinued treatment by herself 1 month after the sequential infusion of two specific, third-generation anti-CD19 and anti-CD22 CAR T cell immunotherapies for refractory/relapsed diffuse large B-cell lymphoma." (PMID 31753002, 2019). "The NCT03196830 phase II trial assessed the role of a DAC-based lymphodepletion regimen preceding CD19 x CD22 TanCAR-T cell infusion in patients with R/R diffuse large B-cell lymphoma (DLBCL)." (PMID 38887285, 2024). "Diffuse large B‐cell lymphoma is the most common type of testicular lymphoma, typically expressing CD19, CD20, CD22, CD79a, and PAX5 markers." (PMID 40735721, 2025). "Diffuse large B‐cell lymphoma typically expresses pan‐B markers CD19, CD20, CD22, CD79a, CD45RA, PAX5 markers, and other markers CD10, BCL6, BCL2, MYC, and MUM‐1." (PMID 40735721, 2025). "CD19, MS4A1 (CD20), and CD22 are specific target antigens for diseases, such as relapsed/refractory large B-cell lymphoma, mantle cell lymphoma, and diffuse large B-cell lymphoma (DLBCL)." (PMID 34975912, 2021). "A vast majority of PCNSL cases are comprised of a diffuse large B cell lymphoma (DLBCL) and express pan-B cell markers CD20, CD19, CD22, and CD79a." (PMID 34771535, 2021). "In contrast to HS, diffuse large B-cell lymphoma constantly express various pan-B markers such as CD19, CD20, CD22, and CD79a, while anaplastic large cell lymphomas are positive for CD30, and ALK." (PMID 17324277, 2007). "More specifically, the use of anti-CD19/anti-BCMA CAR T cells in multiple myeloma and anti-CD19/anti-CD22 CAR T cells in ALL and diffuse large B-cell lymphoma (DLBCL) have both shown enhanced efficacy versus monotherapy." (PMID 34681217, 2021).
diffuse large B-cell lymphoma (continued). "In 11 patients a subpopulation of CD19 CD20 CD22 CD79b-positive B lymphocytes (4%; range 1–22%), with a normal/balanced Ig kappa/lambda ratio evaluated on the CD22-positive population, was identified: 5 PCNSL, 5 diffuse large B-cell lymphoma (DLBCL), 1 follicular lymphoma." (PMID 34150651, 2021).
lupus (22 papers, 2006 to 2025). "For example, CD22 polymorphisms are reported to predispose to autoimmunity, with the low‐expressing allele CD22a found in strains such as the lupus‐prone BXSB mice." (PMID 33728669, 2021). "Deficiency of BCR signal inhibitory coreceptors CD22 and Sialic acid-binding immunoglobulin-type lectin-G (Siglec-G) led to the significant expansions of B-1 cells and MZ B cells, together with lupus-like systemic autoimmune development in mice." (PMID 31795353, 2019). "Furthermore, our ongoing experiments on CD22-deficient mice that develop lupus-like nephritis in association with the production of autoantibodies of IgM class (anti-DNA) rather suggest a pathogenic role of IgM autoantibodies in lupus." (PMID 22355399, 2012). "Epratuzumab, a recombinant monoclonal antibody targeting the CD22 molecule on B cells, has also been administered to lupus patients." (PMID 39937001, 2025). "Several molecules are involved in the transduction, notably CD19, CD20, and CD22, and many have been reported to be altered or defective in lupus patients and lupus animal models." (PMID 37176637, 2023). "Conventional immune suppressive drugs such as cyclophosphamide eliminate activated B cells undergoing cell proliferation, whereas rituximab and epratuzumab, monoclonal antibodies against CD20 and CD22, are used to deplete B cells in human and murine lupus." (PMID 31795353, 2019). "Others studies confirmed that lupus-prone NZB and NZW mice carry the Cd22a allele and later, the expression of a third Cd22 allele, Cd22c, was described in autoimmune prone BXSB mice and the parental SB/Le strain." (PMID 30323814, 2018). "Rituximab, an anti-CD20 monoclonal antibody; ocrelizumab, another anti-CD20 monoclonal antibody; obinutuzumab, a fully humanized anti-CD20 monoclonal antibody; and epratuzumab, a recombinant humanized anti-CD22 monoclonal antibody, have been used in lupus treatment with varied success." (PMID 39937001, 2025). "Despite the evidence implicating CD22 in murine lupus, human genetic studies do not support CD22 as a major disease susceptibility locus in SLE." (PMID 30323814, 2018). "It has been shown that other sialoadhesin molecules related to CD22 have immunoregulatory functions; therefore, in the present study, we addressed the role of epratuzumab on the production of key cytokines by B cells of patients with systemic lupus erythematosus (SLE) and of healthy donors (HD)." (PMID 26183319, 2015). "The published antibodies (Abs) against CD22 on B cells including Epratuzumab could inhibit B cell activation mainly through binding to C2-set Ig domain of CD22, but they are rarely reported to modulate the pathogenic CD4+ T cell function in systemic lupus erythematosus (SLE)." (PMID 23704998, 2013). "B cells play an important role in the pathogenesis of systemic lupus erythematosus (SLE), so the safety and activity of anti-B cell immunotherapy with the humanized anti-CD22 antibody epratuzumab was evaluated in SLE patients." (PMID 16630358, 2006). "Some of the more recent failures in lupus trials include anti-CD20 (rituximab), anti-CD22 (epratuzumab), anti-BAFF (tabalumab, atacicept) CD28-Fc (abatacept), anti-IL6 (PF-04236921), and anti-IFN-α (sifalimumab)." (PMID 39452087, 2024). "In systemic lupus erythematosus (SLE), binding of αM integrins with CD22 downregulated B-cell receptor signaling to maintain autoreactive B-cell tolerance and further inhibited SLE progression." (PMID 37047140, 2023). "Epratuzumab is a humanized IgG1 monoclonal antibody targeting CD22, which is used for the treatment of systemic lupus erythematosus (SLE) by inhibiting autophagy to block activation signals of the B-cell receptor and to promote the internalization of CD-22, thereby suppressing active B cells." (PMID 39559368, 2024).
Burkitt lymphoma (20 papers, 2014 to 2025). A rare form of malignant mature B-cell non-Hodgkin lymphoma. "In another study, one of six (16.7%) adult patients with refractory Burkitt lymphomas was found to develop high-grade CRS after CD19/CD22 CAR T cell infusions." (PMID 35669773, 2022). "We found that salvage therapy with CD19/CD22 CAR T cell infusions or CD19/CD22 CAR T cell infusions combined with ASCT is effective in some adult patients with r/r Burkitt lymphoma." (PMID 35669773, 2022). "In the current study, adult patients with r/r Burkitt lymphoma receiving CD19/CD22 CAR T cell immunotherapy or its combination with ASCT achieved objective response." (PMID 35669773, 2022). "In order to study activity and kinetics of dDT2219 compared with the parental DT2219 form, we performed proliferation assays with CD19 and CD22 positive Burkitt’s lymphoma cell lines Daudi and Raji." (PMID 29316610, 2018). "It is also known that Burkitt lymphoma cells express surface immunoglobulin M and B cell-associated antigens (CD19, CD20, CD22, and CD79a)." (PMID 30233648, 2018). "The SM03 antibody binds to CD22 antigen that expresses on the surface of Burkitt's lymphoma cell lines such as Raji." (PMID 24816427, 2014). "Interestingly, in our study, CD19/CD22 CAR T cell infusions combined with ASCT appeared to lead to more favorable long-term outcomes in adult patients with r/r Burkitt lymphoma." (PMID 35669773, 2022). "Hence, our preliminary results suggest that some adult patients with r/r Burkitt lymphoma can benefit from novel treatment strategies involving CD19/CD22 CAR T cell immunotherapy or its combination with ASCT." (PMID 35669773, 2022). "In Burkitt lymphoma, CD22 is highly expressed on the cell surface." (PMID 28938559, 2017). "This is the first time a NMR-based binding study of high affinity Siglec-2 (CD22) ligands in complex with whole Burkitt’s lymphoma Daudi cells has been described that might open new avenues in developing tailored therapeutics and personalised medicine." (PMID 27808110, 2016). "Notably, a dual-targeting strategy combining 177Lu-based CD22-specific radioimmunoconjugates with rituximab has demonstrated high treatment efficacy in Burkitt’s lymphoma xenograft models, suggesting a synergistic effect between anti-CD22 and anti-CD20 therapies." (PMID 40227793, 2025). "This study explores a novel therapeutic strategy for relapsed/refractory (R/R) Burkitt lymphoma (BL) by integrating autologous hematopoietic stem cell transplantation (ASCT) with tandem anti-CD19/CD22 chimeric antigen receptor (CAR) T cell therapy." (PMID 39717765, 2024). "B-cell markers, including CD22, CD19, CD79a, CD20, Pax5, and germinal center markers, such as CD10 and BCL-6, are expressed in Burkitt lymphoma." (PMID 40115528, 2025). "Another case report of a patient with Burkitt lymphoma, after failing multiple lines of chemotherapy, received donor-derived CD19/CD22 dual-targeted CAR-T cell therapy." (PMID 39844819, 2025). "In detail, 3 out of 6 patients with Burkitt’s lymphoma, who underwent CD19- and CD22-redirected CAR-T therapy, achieved an objective response (two partial responses; one CR)." (PMID 36875091, 2023). "Our preliminary results indicated that salvage therapy with CD19/CD22 CAR T cell infusion alone and that in combination with ASCT are effective in treating some adult patients with r/r Burkitt lymphoma." (PMID 35669773, 2022). "We conducted two single-arm clinical trials to evaluate the clinical efficacy and toxicity of CD19/CD22 CAR T cell immunotherapy both alone (trial A) and in combination with ASCT (trial B) in adult patients with r/r Burkitt lymphoma." (PMID 35669773, 2022). "We conducted two single-arm clinical trials to explore the clinical efficacy and related toxicity of CD19/CD22 CAR T cell immunotherapy alone and in combination with ASCT in adult patients with r/r Burkitt lymphoma." (PMID 35669773, 2022).
Burkitt lymphoma (continued). "In an in vitro experiment mimicking the emergence of CD19 antigen escape of a Burkitt’s lymphoma cell line, AUTO3 was capable of effectively killing, inducing interferon (IFN)-γ secretion and proliferating in response to CD19−/CD22+ Raji targets." (PMID 34642489, 2021). "In human xenograft models of B ALL, of Burkitt’s lymphoma, of DLBCL, and of mantle cell lymphoma, responses to CD22-targeted immunotoxins were greatly enhanced by repeated or continuous administration via surgically implanted osmotic pumps." (PMID 34638774, 2021). "Generally, CD19/CD22 CAR T cell infusions alone appear to be a viable treatment option for adult patients with r/r Burkitt lymphoma without enough HSCs, but the clinical efficacy was relatively limited." (PMID 35669773, 2022). "The recombinant IT showed IC50 values of approximately 2 ng/ml on four Burkitt’s lymphoma cell lines, while being not toxic to CD22-negative cell lines (IC50 > 1,000 ng/ml)." (PMID 34976821, 2021). "To characterize and compare the CD22 promoter activity in cell culture, we analyzed the CD22 expression in two CLL cell lines (JVM-3 and MEC-1) and a non-CLL cell line (BJAB, a human Burkitt lymphoma cell line) at both the protein and mRNA levels." (PMID 40054694, 2025).
multiple myeloma (20 papers, 2019 to 2025). "Preliminary dinical trial resuhs of CD19/CD22 targeted CARs for treatment of ALL/DLBCL and CD19/BCMA targeted for multiple myeloma have demonstrated promising efficacy*'." (PMID 38465225, 2024). "To evaluate myeloma memory B cells, we identified clusters of memory B cells that were either unswitched (UM1–4 clusters; CD19+, IgM+, IgDhet, CD20+, CD22+, and CD27+) or switched (SM1–3 clusters; IgM+, IgD–, CD27het, IgG+, and IgA+)." (PMID 36752202, 2023). "ADCs targeting BCMA are approved in Multiple Myeloma, CD19 in Diffuse large B cell lymphoma (DLBCL) and CD22 in Acute B Lymphoblastic Leukemia (B‐ALL)." (PMID 37740463, 2023). "CD19/CD22, CD19/BCMA, and HER2/IL13Ra2 have been used for the treatment of diffuse B-cell lymphoma, multiple myeloma, and glioblastoma, respectively." (PMID 36765809, 2023). "Comparison of myeloma cells to the two B-lymphoblastoid cell lines also showed CD138/SDC1 and CD28 as characterizing myeloma cells, while CD19, CD22, and CD20 characterized late-stage B-cells." (PMID 35840578, 2022). "Notably, four clinical trials on myeloma, diffuse large B cell lymphoma (DLBCL), melanoma, and NSCLC are ongoing which combine anti-PD1 antibody and IL-17A (NCT03111992), CD22 (NCT03287817), KIT (NCT04493203), or AXL (NCT04681131), respectively." (PMID 38349411, 2024). "Targets expressed in normal bone marrow plasma cells can be divided in those in which expression in myeloma cells remains stable in later stages in longitudinal samples (i.e., CD38, CS1, BCMA, FCRH5, CD74, CD79B), and those for which expression is stage-dependently lost (e.g., CD19, CD22, BAFF-R)." (PMID 38035078, 2023). "Interestingly, the other blood tumor clinical CAR-T target genes, CD22 (in Phase 1 trials) and TNFRSF17 (encoding the BCMA protein and FDA-approved against multiple myeloma), are not essential in any cell line of their respective indications analyzed here." (PMID 37835579, 2023). "This first relates evidently to targets not expressed in all myeloma patients, as being either lost in a subfraction of malignant plasma cells, i.e., BAFF-R, CD19, CD20, and CD22, or gained, i.e., NY-ESO1/2, MUC1, and CD30." (PMID 38035078, 2023).